RN7SL524P (RNA, 7SL, cytoplasmic 524, pseudogene)
Gene: Miscellaneous RNA gene on chromosome 10 (103,974,515 to 103,974,814, reverse strand). Ensembl gene ENSG00000266754.
Homologues: Orthologues: macaque Metazoa_SRP (87% identical), chimpanzee Metazoa_SRP (76% identical). Paralogues in human: RN7SL440P (86% identical), Metazoa_SRP (85% identical), Metazoa_SRP (83% identical), RN7SL718P (82% identical), Metazoa_SRP (81% identical), Metazoa_SRP (80% identical), RN7SL602P (80% identical), Metazoa_SRP (79% identical), Metazoa_SRP (77% identical), Metazoa_SRP (76% identical), Metazoa_SRP (75% identical), RN7SL134P (75% identical), and 713 more.